MMP1 (matrix metallopeptidase 1)
Diseases named in the same sentence as MMP1 in open-access papers (continued):
Sharing a sentence is not in itself a finding about the gene and the disease.
tumor (continued). "In LK0923 tumor cells, FMOD, MMP1 and MMP9 were significantly upregulated after coculture with both 0836CAF and 1001CAF compared to tumor-matched CAFs." (PMID 38822309, 2024). "Previous research has indicated that MMP1 and SERPINE1 can activate PI3K/AKT phosphorylation, promoting tumor progression." (PMID 39551792, 2024). "Our recently published data show that tumor-matched CAFs increased the mRNA expression of MMP1, MMP9 and FMOD in tumor cells when cocultured compared to tumor cells cultured alone in spheroids." (PMID 38822309, 2024). "Matrix metalloproteinases MMP1, MMP2, MMP3 and MMP9, which are involved in extracellular matrix (ECM) remodeling and promotion of tumor cell migration and invasion, were also significantly increased (p < 0.0001) in metastatic cell lines compared to PM cells." (PMID 37047539, 2023). "To demonstrate that the transcriptomic profiles during AOIs selection reflected the histological definition of tumor invasive margin, we evaluated the mRNA levels of MMP1, MMP7, and MMP11 in tumor invasive margin, tumor center, and adjacent normal areas." (PMID 37964075, 2023). "We showed that MMP1 levels, as surrogate markers for the response to treatment, in PAR1CAR-T-cell-treated tumor sections were significantly oriented downward compared to those treated with mock-transduced T cells, non-transduced T cells, and PBS." (PMID 37667257, 2023). "The expressions in the tumor tissues also generally correlated with MIR31HG levels (r = 0.523, r = 0.367, and r = 0.287 for FLNB, LAMA3, and MMP1, respectively)." (PMID 36980216, 2023). "MMP-1 is highly expressed in OSCC and changes the behavior of cancer cells by promoting tumor cells’ invasion." (PMID 36839884, 2023). "We selected four markers that were differentially expressed in normal and tumor human lung tissues: CADM1, KRT16, MMP1, and NAPSA." (PMID 38067281, 2023). "Three target MMP enzymes were selected for the MMP inhibition assay, the collagenase MMP-1, and the gelatinases MMP-2 and MMP-9, which are upregulated in a number of tumor types." (PMID 37108137, 2023). "Previously, it has been documented that MMP-1 and MMP-13 expression is enhanced by TGF-β-activated p38 MAPK pathway in head and neck SCC, promoting collagenolytic and invasive capacity of the tumor cells." (PMID 37864034, 2023). "The PPI network indicated that SSA1 was co-expressed with MMP1, MMP3, and MMP9; together, they played an important role in tumor invasion and metastasis." (PMID 37081987, 2023). "It was also reported that MMP1 was up-regulated in OSCC and accelerated the growth of the tumor and the motility of the cell in OSCC36." (PMID 37185487, 2023). "Low passage tumor alone secreted high concentrations of CCL2/MCP1, CXCL8/IL-8, CXCL1/GRO, IL-6, CXCL10/IP10, G-CSF, TGFβ1, MMP1, CCL3/MIPα, GM-CSF and EGF." (PMID 37063842, 2023). "MMP1, SDC1, SPP1, and CD24 mRNA declaration was much higher in tumor tissues than in non-tumor tissue." (PMID 35037689, 2022). "In BCC's stroma and the peritumoral area, CAFs can secrete an array of MMPs (e.g., MMP-1, MMP-2, MMP-3, MMP-9, MMP-11, MMP-13, MMP-14, MMP-19), all of them promoting ECM remodeling and favoring tumor escape from the anti-tumoral action of the immune cells." (PMID 35572966, 2022). "Tumor malignant phenotype related IGFBP2 and KRT18 were significantly enriched in KRAS-Mut subtype, whereas neutrophils and macrophages related CD177, MMP1 and ARG1 were enriched in WT subtypes." (PMID 35836817, 2022). "MMP1, as a member of MMPs, participates in the EMT which was identified as a strict programmed shift playing a crucial role in tumor invasion and metastasis." (PMID 35948625, 2022). "When correlating MMP-1, MMP-2, MMP-9, TIMP-1, and TIMP-2 expression in tumor tissue in non-invasive and invasive PTC, we report significant positive correlation between TIMP-2 and MMP-2 in the non-invasive tumor group (rho = 0.378, p = 0.039)." (PMID 36551933, 2022).
tumor (continued). "A total of six upregulated genes (FN1, APOA1, CXCL8, MMP1, MMP3, and THBS1) in tumor tissue were identified by the differential analysis of 10 hub genes." (PMID 35719376, 2022). "In conclusion, elevated expression of MMP-1 and TIMP-1 in tumor tissue can predict invasiveness for PTC." (PMID 36551933, 2022). "Multiple MMP family members, such as collagenase 1 (MMP-1), gelatinase A (MMP-2), gelatinase B (MMP-9), matrilysin (MMP-7), and membrane-type (MT)-MMPs, have been correlated with tumor progression such as the formation of metastasis and bad prognosis." (PMID 36366531, 2022). "In tumor spheroids co‐cultured with TIMP‐1‐silenced hASCs, the activities of MMP‐1 and MMP‐9 were significantly higher than those in the control." (PMID 35600659, 2022). "In conclusion, our study revealed a close relationship between high MMP1 expression and poor prognosis in HCC and MMP1 involvement in tumor-immune cell infiltration and immunomodulators." (PMID 35948625, 2022). "While bulk tumor analysis represents a limitation of our study, nonetheless we identified significant upregulation of key TSK signature genes, in particular PLAU, MMP1 and MMP10, ITGA5 in MET vs. PRI- and PRI+ vs. PRI-." (PMID 35480116, 2022). "Seven genes of the prognostic model (COPA, GPX7, ITGB5, MATN3, MCM7, MMP1, and SPP1) have been validated to be related to tumor progression, whereas the remaining three genes, BNDF, GADD45B, and LOX, need to be further analyzed." (PMID 35699863, 2022). "Interactions with endothelial cells through VEGF and matrix metalloproteinase-1 (MMP1) signaling pathways enhanced vascular permeability, which provided favorable conditions for tumor metastasis." (PMID 35454769, 2022). "Among genes significantly downregulated by MEG3 knockdown, as determined by a −2 fold-change from MEG3-knockdown to control, were MMP-1, MMP-9, and MMP-16, three metalloproteases with previously characterized roles in tumor metastasis." (PMID 36231143, 2022). "Single-cell RNA sequencing (scRNA-seq) revealed that MMP1, MMP14 and MMP2 mRNAs were the most abundant MMP family members, and were expressed in epithelial-tumour cells, M2-like macrophages and fibroblastic cells." (PMID 36198801, 2022). "Immunohistochemistry microarray was used to further confirm that protein expression of CD24, MMP1, SDC1, and SPP1 was much higher in tumor sections than in Para cancerous tissues." (PMID 35037689, 2022). "The IL-6 target genes MET, IGF1, MMP3, CEACAM1, MMP1 and WNT5A were upregulated, which enabled the tumour cells to become invasive." (PMID 35022523, 2022). "MMP-1 and MMP-3 had significantly higher salivary levels in OSCC, correlated with tumor stage, compared to the nearly undetectable levels in the saliva of control subjects." (PMID 36547091, 2022). "Exposure to PM2.5 resulted in an increased number of tumor nodules and elevated expression of MMP1, IL-1β, VEGF, and angiogenesis factors in a tumor-bearing mouse model." (PMID 35448437, 2022). "IFI27, LCN2, GAST, and SERPINA1 were downregulated after NACT in tumor cells, while OLFM4, MRPS35, MMP1 and MED21 were upregulated in tumor cells." (PMID 36474268, 2022). "While treatment of GBM cells with either EGF or IFN-γ induces the expression of GBP-1, only EGF treatment induces the expression of matrix metalloproteinase 1 (MMP1) and promotes tumor cell migration/invasion." (PMID 35681772, 2022). "BB94 is a potent extracellular broad-spectrum MMP inhibitor that inhibits MMP-1, MMP-2, MMP-3, MMP-7, and MMP-9 and distant tumor metastases." (PMID 35440570, 2022). "Several studies showed that the MMP-9 level is positively correlated with a higher tumor grade in BC tissue, and TPA mediated tumor invasion and migration by upregulating expression of MMP-1 and MMP-9 in BC cells." (PMID 36119505, 2022).
tumor (continued). "Furthermore, they show that MMP1 levels may correlate with tumor progression." (PMID 36330456, 2022). "Extracellular matrix glycoproteins such as Laminin-γ2 and proteolytic enzymes such as MMP1, CTSS & CTSB were radically up-regulated under acute acidotic stress, but all become less expressed when tumor cells steadily adapted to extended extracellular acidity." (PMID 35410237, 2022). "Our analysis using the HNSC dataset in the TCGA database revealed that the expression of PTGS2, MMP1, and MMP3 in tumor tissues was significantly higher." (PMID 36555343, 2022). "The overexpression of IL1A can, in turn, stimulate the transcription of growth factors such as MMP1 or VEGFA, both found upregulated in our tumor samples, possibly creating a proper environment for carcinogenesis." (PMID 34638231, 2021). "Based on the TCGA and GTEx data, we found that MMP1, MMP3, MMP7, MMP9, MMP12, MMP13 all increased in the tumor as compared with the normal esophageal tissues." (PMID 34559117, 2021). "The analysis includes comparison of the three targets (CDK2, MMP1, and HSP90) between 408 stomach adenocarcinoma (STAD) samples and non-tumor stomach tissues." (PMID 33921173, 2021). "In particular, we found increased relative expression of MMP1, COL6A1, COL6A3, and TGFB1 in MCTS relative to tumor spheroids." (PMID 34035369, 2021). "The protein concentrations of MMP-1, MMP-2, MMP-3, and MMP-9 also have been seen to be greater in OSCC tumor tissue in contrast to control tissue." (PMID 33892690, 2021). "AIM2 knockout in cSCC cells led to decreased expression of invasive proteases MMP1 and MMP13, thereby weakening the invasion of tumor cells." (PMID 34104103, 2021). "The expression levels of CXCL10, IGF1, MMP3, MMP1, ICAM1, and IL-13 were significantly up-regulated in tumor tissues." (PMID 34544905, 2021). "Additionally, low levels of NO are able to activate matrix metalloproteinases (MMP-1, -9, -13), which degrade the components of the extracellular matrix and paves the way for tumor cell dissemination outside of the tumor and endothelial cells into the tumor core for blood vessel formation." (PMID 33513777, 2021). "In BC, numerous subtypes of MMPs containing MMP1, MMP7, MMP9 and MMP11 have investigated a positive correlation between increased levels of MMPs and tumour progression." (PMID 34142438, 2021). "The confocal fluorescent images show that MMP1 and FAK signals are visible at the tumor front indicated with the white arrows in inset of Fig 2C1." (PMID 33513131, 2021). "We found that MMP1, MMP3, MMP7, MMP9–MMP12, and MMP14 were significantly upregulated in tumor tissue, while MMP28 was significantly downregulated in tumor tissue." (PMID 34804973, 2021). "Necrosis can release cancer-promoting factors like MMP1, HMGB1, and ICAM1, which induce microenvironment changes resulting in tumor aggressiveness." (PMID 34084172, 2021). "In vivo experiments further validated that lnc-KASRT enhanced tumor growth and reduced tumor apoptosis; meanwhile, it also increased tumor KLF6-SV1, MMP-1, and MMP-9 expressions but decreased tumor SRSF1 and KLF6-WT expressions in xenograft mice." (PMID 34568030, 2021). "Thus, the increase in MMP1 and MMP3 expression observed after the knockdown of the ELOVL5 and IGFBP6 genes is consistent with the hypothesis that ELOVL5 and IGFBP6 are associated with tumor metastatic potential." (PMID 34149804, 2021). "Further analysis of differences in the gene expression levels of ADAM12, MMP1, SERPINE1, PLOD3, and P4HA3 between tumor and adjacent normal tissues in 18 cancer types from TCGA were examined." (PMID 34121340, 2021). "We found that MMP1, MMP3, MMP7, MMP9-MMP12, and MMP14 were significantly upregulated in tumor tissue, while MMP15–MMP17, MMP19–MMP21, MMP23A, MMP23B, and MMP25–MMP28 were significantly downregulated in tumor tissue." (PMID 34804973, 2021).
tumor (continued). "They illustrate the fact that BAI1-expressing tumor cells had lower expression of VEGF and MMP-1, which is known to be a positive regulator of tumor angiogenesis." (PMID 34298774, 2021). "MMP1, MMP3, MMP7, MMP12, and MMP13 belong to the matrix metalloproteinase family, and MMPs were able to participate in the tumor metastasis process by degrading the ECM." (PMID 34381520, 2021). "The study also showed important differences in the levels of mRNA and protein overexpression of MMP-1, MMP-3 and MMP-9 in the tumor tissue compared to normal skin." (PMID 34204372, 2021). "It has been reported that high levels of matrix metalloproteinases, such as MMP-1, MMP-2, MMP-9, and MMP-14, produced by tumor cells participate in VM37." (PMID 33850110, 2021). "Studies have shown that the anti-tumor effect of 5-FU has a certain correlation with PTGS2, NR3C2, CA2 and MMP1." (PMID 34125845, 2021). "The transcription factor AP1, which consists of c-Jun and c-Fos, plays an important role in controlling MMP1, MMP9, and MMP12 expression in tumor cells." (PMID 33958583, 2021). "Precisely, we analyze the distributions of MMP1, integrins, and FAK and their localization in relation to the tumor membrane density." (PMID 33513131, 2021). "MMP-1 and MMP-2 were expressed both in tumor cells and normal epithelial cells, but their activity was higher in BCC compared to normal skin." (PMID 34204372, 2021). "In the furthermore bioinformatics analysis, we found that MMP1, MMP3, MMP7, MMP9, MMP12, MMP13 all increased in the tumor as compared with the normal esophageal tissues." (PMID 34559117, 2021). "The co-expression of MMP1 and PAR1 is strongly related to tumor stage, lymphatic metastasis and tumor recurrence in human cancer." (PMID 34753916, 2021). "It has been shown that some members of the family of MMPs promote tumor growth, angiogenesis, epithelial–mesenchymal transition (EMT), and premetastatic niche formation in cancer patients, as is the case with MMP-1, MMP-2, MMP-3, and MMP-9." (PMID 34445715, 2021). "When investigating the mRNA expression of COL1A2, POSTN, GREM1, MMP1, and MMP9 in patient material, we found all five genes to be upregulated in HNSCC tumor tissue compared to normal oral tissue." (PMID 34283070, 2021). "We found that, the transcriptional level of MMP1, MMP3, MMP7, MMP9–MMP12, and MMP14 in tumor were significantly upregulated, both in public database and in our samples." (PMID 34804973, 2021). "MMPs lacking a transmembrane domain are expressed on the surface of other cells including MMP‐1 on keratinocytes, MMP‐2 on the surface of endothelial cells, fibroblasts, and tumor cells, and MMP‐8 and MMP‐9 on the surface of PMNs." (PMID 33656791, 2021). "JNK promotes the expression of Mmp1, which acts as an enzyme to degrade basement membrane and ECM components to promote tumor cell motility." (PMID 32098783, 2020). "Expression of LMP1 has been shown to induce MMP1 and MMP9 implicating the viral oncoprotein in contributing to tumor metastasis." (PMID 33382850, 2020). "Among all MMPs, MMP-1, MMP-2, MMP-3, MMP-7, and MMP-9 are involved in almost all stages of tumor growth, angiogenesis, and metastasis." (PMID 32685465, 2020). "Among them, the expressions of MMP1, MMP3, and MMP10 in tumor tissues were higher than those in normal tissues (p < 0.05)." (PMID 32636440, 2020). "The results were displayed a heatmap, which showed the expression levels of P3H1, SPP1, MMP1, LGALS1, and ITGB5 in tumor tissues and normal tissues." (PMID 32951492, 2020). "The matrix metallo-protease MMP1 has been used as a marker of epithelial to mesenchymal transition (EMT) and neoplastic transformation in Drosophila tumor models." (PMID 32737120, 2020). "VEGFC can, thus, be added to a growing list of tumor and metastatic proteins, including CXCR4 and MMP1, all of which are transcriptionally regulated by BACH1." (PMID 32132179, 2020).
tumor (continued). "When pdsw-RNAi was co-expressed in hipk-overexpressing cells, tumor-like growth, JNK phosphorylation and MMP1 induction were significantly suppressed." (PMID 33199523, 2020). "CAFs can secrete ECM components (such as type I collagen or fibrin) and several soluble factors, such as growth factors (EGF, HGF, TGF-β), metalloproteinases (MMP-1, -2, -9) or chemokines (CXCL12), to promote tumor growth and metastasis." (PMID 32984031, 2020). "An IHC staining of MMP-1 was also performed and the positive staining percentage of MMP-1 per tumor area was calculated." (PMID 31726667, 2019). "Knockdown of HPSE is accompanied by downregulation of MMP1, MMP7, MMP10, and MMP13, all of which are directly involved in the degradation of extracellular matrix and facilitate tumor cell invasion." (PMID 31001480, 2019). "Specific molecules which have the role of degrading proteins are called matrix metalloproteinases and are released in the tumor environment by tumor cells (MMP7, 14, 15, and 16), inflammatory cells (MMP12), and fibroblasts (MMP1, 2, 3, and 13)." (PMID 31934531, 2019). "It has been reported that MMP1 overexpression has an important role in promoting tumor cell invasion and HMGCS2 silence promoted tumor cells metastatic via Epithelial-Mesenchymal Transition (EMT) process and the activation of ERK/c-Jun signaling pathway." (PMID 31074374, 2019). "Overexpressed proteolytic enzymes MMP1 and MMP3 romote tumor growth and vascularization by enhancing extracellular matrix degradation in tumor cell microenvironments." (PMID 31717665, 2019). "Recently, the development of MMPIs has moved away from general MMPIs towards specific inhibitors for MMP1, gelatinases, MMP11 and specific cancers or stages of tumor progression." (PMID 31514474, 2019). "U. dioica extract treatment decreased miR-21 expression, which substantially reduced the overexpressed MMP1, MMP9, MMP13, vimentin and CXCR4, and increased E-cadherin in the treated tumor cell lines." (PMID 31362429, 2019). "The elevation of MMP-1 was due to CAF-derived soluble factors, and MMP-1 can cooperate with other MMPs in the ECM to protect tumor cells from CTX-induced growth inhibition." (PMID 30927928, 2019). "Among the MMPs, MMP1, MMP2, MMP9 and MT1-MMP produced by both stromal and tumor cells degrade and migrate through the ECM." (PMID 30241395, 2018). "The results proved that apigenin and luteolin inhibited MMP1 expression and CYP1A1 activity, which trigger the retraction of the adjacent LEC barrier thereby enabling MDA-MB231 tumor spheroid intravasation." (PMID 29593542, 2018). "To better elucidate the role of MMP‐1/IGF2/IGFBP2 in MSC tumor tropism, we analyzed the expression of IGFBP2 in MSCs with different tumor‐tropic properties by western blot analysis." (PMID 29321953, 2018). "Our data show significantly upregulated levels of MMP-1, MMP2, MMP3 and MMP9 mRNA in ESCC tumor tissues compared to the adjacent normal tissues." (PMID 30241395, 2018). "It is therefore possible, that reduction in MMP13 and MMP1 production after AIM2 knockdown impairs implantation of cSCC cells in the skin of SCID mice and this way results in delay in tumor growth." (PMID 28526809, 2017). "Tumor growth and invasion in breast cancer gland xenograft models require thrombin-induced interplay between ErbB and EGFR, or by MMP-1-induced fibroblasts derived Ca2+ signaling." (PMID 29291033, 2017). "MMP-1 was noted because it contains a putative target sequence of miR-361-5p in the 3’UTR and it was closely correlated with tumor cell invasion." (PMID 29132384, 2017). "In this study, we observed that the levels of MMP-1, MMP-2, and MMP-10 significantly increased in co-cultures of tumor cells/monocytes, and we have previously shown that this correlates with increased collagen degradation." (PMID 28337194, 2017). "MMP-1, MMP-2 and MMP-9 were all increased in tumor samples compared with matched, corresponding normal tissues." (PMID 28915603, 2017).